TSPAN9 (tetraspanin 9)
Diseases named in the same sentence as TSPAN9 in open-access papers (continued):
Sharing a sentence is not in itself a finding about the gene and the disease.
liver cancer (2 papers, 2016 to 2020). An epithelial or non-epithelial malignant neoplasm that arises from the liver. "Two of these genes (TSPAN9, CYTH3) were directly correlated with cancer, with CYTH3 identified as a biomarker in liver cancer." (PMID 27478834, 2016).
adrenocortical carcinoma (1 paper, 2022). "However, the hazard ratios remained zero with the stepwise addition of ITGA4, EMILIN1, and TSPAN9 to the Cox model in adrenocortical carcinoma, kidney renal papillary cell carcinoma, and mesothelioma." (PMID 35739492, 2022).
alcoholic cirrhosis (1 paper, 2024). "Hypermethylated DMRs observed in alcoholic cirrhosis and alcoholic HCC were found in forkhead box K1 (FOXK1), zinc finger CCCH-type containing 3 (ZC3H3), nuclear factor IX (NFIX), histone deacetylase 4 (HDAC4), and tetraspanin 9 (TSPAN9) genes." (PMID 38302914, 2024).
diabetes (1 paper, 2016). "The previously identified UMOD locus showed genome-wide significant association with eGFRcrea among those with diabetes (rs12917707, P value=2.5 × 10−8), and six loci (NFKB1, UNCX, TSPAN9, AP5B1, SIPA1L3 and PTPRO) had nominally significant associations with eGFRcrea among those with diabetes." (PMID 26831199, 2016).
gastric tumors (1 paper, 2022). "The hazard ratio of CAF infiltration in COL1A1, COL5A1, ITGA4, EMILIN1, and TSPAN9 signature was even higher, presenting a 36.8 times higher risk of death in gastric tumors with high CAF infiltration." (PMID 35739492, 2022).
hypomania (1 paper, 2020). "Located within the same 12p13.33 region, the genes DCP1B, TSPAN9, and FKBP4 also overlapped between hypomania and schizophrenia, and have previously been associated with a range of physical health phenotypes including obesity and waist–hip ratio." (PMID 32152294, 2020).
lymph node metastasis (1 paper, 2022). "Higher EV CD59 levels were significantly correlated with distant metastasis (p = 0.0475), and higher EV TSPAN9 levels were significantly associated with lymph node metastasis (p = 0.0011), distant metastasis at diagnosis (p = 0.0104) and higher TNM stage (p = 0.0065)." (PMID 36612172, 2022). "Finally, we explored the potential association of plasma-derived EV levels of ADAM10, CD59, TSPAN9 and plasma CEA with different clinicopathological characteristics, including gender, age, TNM stage, tumor stage, lymph node metastasis and distant metastasis, of enrolled CRC patients." (PMID 36612172, 2022).
ovarian carcinoma (1 paper, 2021). A malignant neoplasm originating from the surface ovarian epithelium. "HMOX2, ICMT, MICU1, and TSPAN9 also positively correlated with CD73_1 and CD73_2 densities and short survival and have been shown to be involved in conferring chemoresistance in ovarian cancer." (PMID 33917869, 2021).
Sepsis (1 paper, 2024). Sepsis is defined as life-threatening organ dysfunction caused by a dysregulated host response to infection. "The Tspan9‒/‒ mice also showed lower immune response compared to the WT mice at early stages, indicating that toxin-mediated severe sepsis is largely prevented if migracytosis function gets impaired." (PMID 39500876, 2024). "Lastly, we demonstrated that the migracytosis-defective Tspan9‒/‒ mice show much lower and delayed immune responses compared to the WT mice upon systematic exposure to TcdB3, suggesting that the non-canonical migracytosis is prominent to the toxin-induced sepsis." (PMID 39500876, 2024).
stomach adenocarcinoma (1 paper, 2022). "All this data suggested COL1A1, COL5A1, ITGA4, EMILIN1, and TSPAN9 as a poor prognostic CAF signature with high specificity to stomach adenocarcinoma." (PMID 35739492, 2022). "Strikingly, the correlation of EMILIN1 and TSPAN9 with CAF infiltration was quite strong in stomach adenocarcinoma compared to a poorer correlation in the other three cancers." (PMID 35739492, 2022). "With further analysis, we revealed COL1A1, COL5A1, ITGA4, EMILIN1, and TSPAN9 as a poor prognostic gene signature for CAF infiltration, with high specificity to stomach adenocarcinoma." (PMID 35739492, 2022). "This was in parallel to the increase in the poor prognostic impact of CAF infiltration by stage in stomach adenocarcinoma, suggesting a stage and CAF dependent role for ITGA4, EMILIN1, and TSPAN9." (PMID 35739492, 2022). "Despite that, adding TSPAN9 to the COL1A1, COL5A1, ITGA4, and EMILIN1 Cox model further increased the hazard ratio to 36.813 for CAF infiltration in stomach adenocarcinoma samples." (PMID 35739492, 2022). "Our investigation of TCGA stomach adenocarcinoma data does not suggest either a poor or a good prognostic role for EMILIN1 or TSPAN9 per se." (PMID 35739492, 2022). "The KM-survival analysis did not indicate a prognostic role for ITGA4, EMILIN1, or TSPAN9 in stomach adenocarcinoma per se." (PMID 35739492, 2022). "Based on the comparative pan-cancer analysis of these key CAF markers and a comprehensive literature search we identified COL1A1, COL5A1, ITGA4, EMILIN1, and TSPAN9 as the signature genes, which potentiated the poor prognostic impact of CAF infiltration specifically in stomach adenocarcinoma." (PMID 35739492, 2022).
tumor (22 papers, 2015 to 2025). "Through Western blotting, we found that Tspan9 overexpression was associated with marked FN1 upregulation in these OS tumor cells." (PMID 35280793, 2022). "TSPAN9, a 4-transmembrane protein involved in tumor growth and signal transduction, has been shown to be linked to tumor invasion, metastasis, and autophagy." (PMID 36612172, 2022). "TSPAN9 suppresses the ERK1/2 pathway to downregulate the proteins associated with tumor metastasis including matrix metalloproteinase-9 (MMP-9) and urokinase plasminogen activator (uPA)." (PMID 34222025, 2021). "Conversely, Tspan7, CD82, CD63, Tspan7, and Tspan9 are downregulated, suppressing digestive system tumor cell metastasis." (PMID 38389703, 2024). "The fibroblast compartment showed significant overexpression of TSPAN9, indicating its potential role in tumor invasion and metastasis in stage 4 primary CC." (PMID 38255741, 2024). "Tspan29, Tspan30, and Tspan9, in exosomes, provide potential biomarkers for distinguishing tumor types, aiding in diagnosis and prognosis." (PMID 38649381, 2024). "TSPAN9 was specifically overexpressed in the fibroblast compartment, suggesting involvement in tumor invasion and metastasis." (PMID 38255741, 2024). "The mechanisms whereby Tspan9 achieves these regulatory activities, however, have yet to be defined, particularly in other tumor types." (PMID 35280793, 2022). "In conclusion, our results indicated that hsa-miR-9-5p-mediated downregulation of TSPAN9 was associated with poor HCC prognosis, immune-related signaling pathway, and tumor immune infiltration." (PMID 35600044, 2022). "Recent experimental evidence suggests that the transmembrane protein tetraspanin-9 (Tspan9) plays a role in tumor development." (PMID 35280793, 2022). "Herein, we assessed Tspan9 expression in OS and found it to be upregulated in both OS patient tumor tissues and in OS cell lines." (PMID 35280793, 2022). "Tumor lung metastasis were significantly impaired in mice implanted with HOS cells in which Tspan9 was downregulated as compared to mice implanted with control HOS cells." (PMID 35280793, 2022). "Our results showed that the patients with ncRNAs mediated TSPAN9 downregulation had a poor prognosis and tumor immune infiltration." (PMID 35600044, 2022). "Tspan9 can further enhance tumor cell 5-fluorouracil resistance via the inhibition of the PI3K/Akt/mTOR pathway and the induction of autophagic activity." (PMID 35280793, 2022). "TSPAN9, a 4-transmembrane protein that plays an important role in tumor progression and signal transduction, has been found to be closely related to tumor invasion, metastasis, and autophagy." (PMID 31911756, 2020). "Second, TSPAN9 (tetraspanin-9) belongs to a protein superfamily that is involved in cell development, differentiation, mobility, as well as in tumour proliferation and invasion." (PMID 32019179, 2020). "While transmembrane proteins are closely related to integrins, TSPAN9 has been found to inhibit EMT in tumor cells, and the role of integrins in this warrants further exploration." (PMID 31242895, 2019). "By regulating the expression of TSPAN9 in GC cells in vitro, it was found to modulate tumor EMT and migration." (PMID 31242895, 2019). "In summary, in the present study we highlighted the roles of EMILIN1 and TSPAN9 in tumor cell regulation and the mechanisms involved in TSPAN9-mediated cell migration and invasion." (PMID 31242895, 2019). "The extracellular secretory protein EMILIN1 can increase this tumor suppressive effect by promoting the expression of TSPAN9." (PMID 31242895, 2019). "Tspan9 expression was significantly negatively correlated with tumor immune-cell infiltration and the immune checkpoint CTLA4, Tspan9 can decrease tumor immune-cell infiltration, enrich immune-related signaling pathways, and express immune checkpoint proteins to exert its tumor suppressor effects." (PMID 38649381, 2024).
tumor (continued). "Thirdly, our results suggested that TSPAN9 may play its tumor-suppressor role by reducing tumor immunocyte infiltration, enrichment of immune-related signaling pathway, and expression of immune checkpoint proteins in HCC patients." (PMID 35600044, 2022). "In this way, the relevance within TSPAN9 and tumor immunity was then explored." (PMID 35600044, 2022). "Given that different TM4SF proteins play distinct roles as suppressors or promoters of oncogenesis in a context-dependent manner, however, it is impossible to reliably predict the functional role of Tspan9 as a regulator of OS tumor cell survival, migration, or metastasis." (PMID 35280793, 2022). "However, the poor prognostic effect of EMILIN11 and TSPAN9 was surprising since EMILIN-1 is regarded as a tumor suppressor which acts synergistically with TSPAN9." (PMID 35739492, 2022). "In previous studies, TSPAN9 was found to be involved in tumor invasion and metastasis." (PMID 31911756, 2020). "In addition to identification of plasma EV CD59 and TSPAN9 as a two-marker panel for CRC detection, the pathobiological roles of EV CD59 and TSPAN9 in the tumor microenvironment and/or chemoresistance of CRC obviously remain as intriguing issues that warrant further investigation." (PMID 36612172, 2022). "Hence, the potential upstream lncRNAs of the hsa-miR-9-5p/TSPAN9 axis could be the tumor-suppressor lncRNAs in HCC." (PMID 35600044, 2022). "Therefore, we speculate that EMILIN1 itself does not play a major role in tumor suppression, but through synergy with TSPAN9 to exert a anti-tumor effect." (PMID 31242895, 2019). "Moreover, EMILIN1 can synergistically boost the tumor suppressive effect of TSPAN9, which may be produced by promoting TSPAN9 expression." (PMID 31242895, 2019). "We additionally overexpressed Tspan9 in U2OS cells which expressed low endogenous Tspan9 levels, and found that the upregulation of this tetraspanin increased tumor cell migratory and invasive activity." (PMID 35280793, 2022). "Moreover, EMILIN1 could promote the tumor-suppressive effect of TSPAN9." (PMID 35600044, 2022). "No studies to date have clarified the functional importance of Tspan9 in OS, and the mechanistic role of this tetraspanin in this cancer remains to be elucidated, particularly in the context of EMT induction and tumor metastasis." (PMID 35280793, 2022). "The expression levels of PHTF2, MFAP2, INHBA, TSPAN9, and CCL26 (p < 0.05) displayed tumor stage-dependent alterations." (PMID 34456964, 2021). "We further analysed the methylation status of VWCE, TSPAN9 and ADAM12 genes in 45 adjacent-to-tumour tissues." (PMID 32019179, 2020). "Tetraspanin 9 (TSPAN9), a member of four transmembrane protein superfamily that plays an important role in tumor progression, has shown regulatory effects on proliferation, migration, invasion, and autophagy." (PMID 33344463, 2020). "Our experiments have found that TSPAN9 can inhibit the RAS/ERK pathway, thereby inhibiting tumor invasive and metastatic potential." (PMID 31242895, 2019). "All these results suggested that the synergistic anti-tumor effects of EMILIN1 and TSPAN9 are achieved by increasing the expression level of TSPAN9." (PMID 31242895, 2019). "For instance, if we could find a way to reduce the expression of TSPAN9 or restore the expression of TSPAN14, it might help to inhibit further progression of the tumor." (PMID 37516981, 2023). "Moreover, significant differences were found in the expressions of INHBA, CCL26, MFAP2, TSPAN9, and PHTF2 in tumor stage based on TCGA-ESCA, suggesting their prognostic value in ESCC tumor development." (PMID 34456964, 2021). "Since the expression level of TSPAN9 in tumor cells is lower than that of normal cells, simply increasing the expression of EMILIN1 in tumor cells does not promote the expression of TSPAN9." (PMID 31242895, 2019).
tumor (continued). "A study focused on uncovering clinically significant aberrantly methylated genes in tumor cells reported three genes to be exclusively hypomethylated in TNBC, specifically Von Willebrand factor C and Epidermal Growth Factor domain-containing protein (VWCE), tetraspanin-9 (TSPAN9), and ADAM12." (PMID 38473804, 2024). "Besides that, expression of TSPAN9 held a significantly negative correlation with tumor immunocyte infiltration as well as immune checkpoint CTLA4." (PMID 35600044, 2022). "In contrast, here, we described a higher level of expression of TSPAN9 in TNBC than in non-neoplastic counterparts, suggesting that TSPAN9 might have a tumour-dependent molecular status and role." (PMID 32019179, 2020). "Therefore, we believe that the synergistic anti-tumor effect of EMILIN1 and TSPAN9 is mainly achieved by TSPAN9.We further found that simultaneous overexpression of EMILIN1 and TSPAN9 more significantly inhibited the FAK-RAS-ERK1/2 pathway as compared to the overexpression of TSPAN9 alone." (PMID 31242895, 2019). "The genes Fam65b and Il1r1 were methylated preferentially in the non-tumor liver tissue, whereas the genes Synpo and Tspan9 were methylated preferentially in tumors; the gene Srd5a2 in each half of the tested tumors was preferentially methylated in either the non-tumor tissue or in tumors." (PMID 25918251, 2015). "We observed that TSPAN9 and ADAM12, but not VWCE, protein levels were significantly higher in tumours than in non-neoplastic tissues (p < 0.05)." (PMID 32019179, 2020). "We confirmed that TNBC tumours had significantly lower methylation levels than non-neoplastic samples in all analysed CpGs in VWCE, TSPAN9 and ADAM12 (p < 0.05)." (PMID 32019179, 2020).
cancer (15 papers, 2015 to 2024). A tumor composed of atypical neoplastic, often pleomorphic cells that invade other tissues. "Conversely, the overexpression of Tspan9 enhanced the metastasis of these cells, confirming its carcinogenic role in this cancer type." (PMID 35280793, 2022). "In this context, we are also the first to explore the clinical significance of plasma EV levels of CD59 and TSPAN9 in cancer." (PMID 36612172, 2022). "There are few studies on TSPAN9 in cancer, and existing research has focused on its role in inflammation." (PMID 31911756, 2020). "Additionally, Tspan9 overexpression has been shown to inhibit the motility and aggressiveness of cancer cells by inhibiting the EMT process and blocking the activation of the FAK/Ras/ERK pathway." (PMID 38389703, 2024). "Since autophagy has been found to be involved in cancer cell resistance, we investigated whether TSPAN9 enhances autophagy levels." (PMID 31911756, 2020). "Our research suggests that TSPAN9 may be a novel mechanism for inducing drug resistance in cancer cells." (PMID 31911756, 2020). "TSPAN9 is probably directly related to the proliferation of cancer cells." (PMID 27478834, 2016). "Moreover, our results provide a plausible explanation for TSPAN9 deregulation in cancer, as we demonstrated that aberrant TSPAN9 methylation could regulate its expression in TNBC." (PMID 32019179, 2020). "Therefore, we have highlighted the role of EMILIN1 and TSPAN9 in cancer progression." (PMID 31242895, 2019). "More interestingly, seven different genes (ECH1, PEX5, MLF2, NFIX, TSPAN9, SAMD4B, and NFKBIB) were associated with another drug C646, which is a small molecule inhibitor targeting histone acetyltransferase p300, an enzyme that alters the cancer transcriptome in the lung, colon and pancreas." (PMID 29207666, 2017).
infection (5 papers, 2013 to 2025). The state of being infected such as from the introduction of a foreign agent such as serum, vaccine, antigenic substance or organism. "Tspan9 has recently been identified as a novel host factor for the infection of the U2OS osteocarcinoma cell line with alphaviruses." (PMID 28032533, 2017). "Fusion of prebound SINV-GFP or SFV with the plasma membrane bypassed the requirement for clathrin, FUZ and TSPAN9 in infection, suggesting that like clathrin, FUZ and TSPAN9 are involved in virus entry steps." (PMID 24367265, 2013). "FUZ and TSPAN9 were broadly required for infection by the alphaviruses Sindbis virus, Semliki Forest virus, and Chikungunya virus, but were not required by the structurally-related flavivirus Dengue virus." (PMID 24367265, 2013). "Depletion of clathrin, ARCN1, FUZ or TSPAN9 significantly inhibited infection by both viruses, thus demonstrating a requirement for these proteins during alphavirus infection of primary human cells." (PMID 24367265, 2013). "Our data demonstrated that ARCN1 depletion blocked alphavirus-cell binding, and identified two novel host factors, FUZ and TSPAN9, that promote alphavirus entry and infection." (PMID 24367265, 2013). "Host factors, including TIM-1, FHL1, and TSPAN9, are known to facilitate CHIKV entry and promote infection, whereas others, such as IFITM3, inhibit viral adsorption by limiting membrane fusion and virion internalization." (PMID 39917312, 2025). "Although direct binding of CHIKV particles to TSPAN9 has not been demonstrated, TSPAN9 depletion has been shown to strongly inhibit infection not only of alphaviruses but also of vesicular stomatitis virus (VSV)." (PMID 31752346, 2019). "In contrast, while infection by the flavivirus Dengue virus 2 (DENV2) was inhibited by clathrin or ARCN1 depletion and was dependent on endosomal acidification (data not shown), it was resistant to depletion of either FUZ or TSPAN9." (PMID 24367265, 2013).
digestive tumors (1 paper, 2024). "Generally, the expression of Tspan7, CD82, Tspan9, and CD63 are downregulated suppress the migration and invasion of digestive system tumor cells." (PMID 38389703, 2024).
TSPAN9 also shares sentences with these, for which no sentence is quoted: autoimmune thyroid disease (1 paper); breast carcinoma (1); Cirrhosis (1); colon cancer (1); Fever (1); mesothelioma (1); non-small cell lung carcinoma (1); Obesity (1); schizophrenia (1); Stroke (1).